EGFR (epidermal growth factor receptor)
Diseases named in the same sentence as EGFR in open-access papers (continued):
Sharing a sentence is not in itself a finding about the gene and the disease.
cancer (continued). "This significant rise might reflect several factors, including better cancer survival rates; an aging population; and the impact of cancer treatments, such as EGFR inhibitors, which can cause high blood pressure, on cardiovascular health." (PMID 39044884, 2024). "Whether mutations in CAMs and EGFR contribute to the development of human diseases, including cancer, by affecting the CAM-dependent regulation of EGFR is an important question for further research." (PMID 39594667, 2024). "Applying mechanical actuation in a human model of non-small-cell lung cancer (NSCLC) revealed that cancer cell responses were affected by physical cues associated with breathing motions, mediated by changes in signaling through epidermal growth factor receptor (EGFR) and MET protein kinase." (PMID 39459070, 2024). "A recent study suggested that exosomes can transfer wild-type EGFR, which, upon internalization by EGFR-mutated cancer cells, activates downstream PI3K/AKT and MAPK signaling pathways, thereby conferring osimertinib resistance to EGFR-mutated sensitive cancer cells both in vitro and in vivo." (PMID 39403600, 2024). "SHERLOCK enables to identify EGFR-T790M mutation in patient DNA with high efficiency by detecting 0.6% mutant ratio samples, this system was also used for DNA and RNA detection with single-base specificity and attomolar sensitivity in cancer patients samples." (PMID 38816739, 2024). "However, gene amplification and activating mutations in EGFR have been frequently observed in many human cancers, including lung adenocarcinomas." (PMID 39470734, 2024). "In cancer, it may apply to the suppression of osimertinib resistance in EGFR‐mutated sensitive cancer cells." (PMID 39479633, 2024). "EGFR overexpression, mutation, or both contribute to the malignant phenotype of many cancer cells." (PMID 39051331, 2024). "Co‐culture and conditioned medium experiments demonstrate that PCs reduce TKI effectiveness in EGFR‐mutated cancer cells, a reversible phenomenon through silencing IL32 expression in PCs or depleting the IL32 receptor β5‐integrin on cancer cells, thereby restoring cancer cell sensitivity." (PMID 39435643, 2024). "EGFR/Her2 dysregulation or amplification is associated with poor prognosis in several cancer types." (PMID 39426288, 2024). "Thus, molecular analyses suggest the presence of very rare cells harboring shared EGFR mutations within normal lung tissues of patients with potentially mosaic-derived EGFR-mutant cancers." (PMID 39406916, 2024). "Loss of PTPRS function through mutation or deletion has been shown to increase TKI resistance in multiple human preclinical cancer models and has been linked with worse overall survival and more rapid disease progression in patients with EGFR-driven lung cancer." (PMID 38049664, 2024). "Similarly, KRAS mutations, particularly the pathogenic c.35G>T (p.Gly12Val) variant identified in this study, are well-known drivers of cancer and are associated with resistance to certain therapies, such as anti-EGFR monoclonal antibodies." (PMID 39296440, 2024). "It is established that aberrant cancer cell proliferation is associated with EGFR overexpression." (PMID 38431714, 2024). "Based on gene expression, EGFR has been investigated to be a targetable cancer-associated marker that may serve to define patient subgroups potentially suitable for EGFR-directed therapy approaches." (PMID 38772416, 2024). "Molecular testing using cancer gene panel sequencing had been performed on plasma (a 105 gene panel) and the diagnostic biopsy tissue (a 648 gene panel), both of which revealed a gain-of-function EGFR exon 19 indel (L747_E749del)." (PMID 39057170, 2024). "Consequently, the developing of second-generation EGFR TKIs, for example dacomitinib and avitinib, was aimed at specifically targeting cancers harboring both the EGFR-activating mutations and T790 M mutation." (PMID 39091946, 2024).
cancer (continued). "Besides the secondary EGFR mutations, amplification, loss, and mutation of some other cancer-related genes also contribute to gefitinib resistance, such as MET, HER2, BRAF, and PIK3CA." (PMID 38472205, 2024). "In conclusion, the future outlook for EGFR-TKI-induced cardiotoxicity involves personalized treatment approaches, improved risk prediction, and more effective therapeutic strategies, ultimately enhancing the quality of life and survival prospects for individuals with EGFR-mutated cancers." (PMID 39211774, 2024). "Thus, identifying these EGFR germline mutations is crucial for screening family members for potential cancer risks." (PMID 39160638, 2024). "Although our research did not include assessing the impact of immunotherapy, when examining the association of EGFR mutations with smoking, we observed that cancer patients with EGFR mutations had a significantly lower tobacco cigarette consumption than those with wild-type EGFR." (PMID 39199673, 2024). "Therefore, genetic mutations affecting EGFR activity stand among the main causes of the progression of numerous human cancers." (PMID 36790582, 2024). "Aberrant activation of the EGFR, arising from autocrine ligand–receptor stimulation, point mutations, deletions, and gene amplification, is associated with a poor prognosis in a large number of human malignant tumors." (PMID 39780846, 2024). "EGFR mutations are prevalent in each of these cancers; therefore, patients with these cancers may benefit from a pan-cancer vaccine that targets common EGFR mutations." (PMID 38675381, 2024). "In addition, the EGFR mutations and the single nucleotide polymorphism (SNP) of Aurora kinase A are associated with earlier tumor stages of several cancers." (PMID 39682093, 2024). "EGFR staining intensity is significantly associated with cancer-specific survival." (PMID 39594688, 2024). "In addition to tyrosine kinase inhibitors for EGFR‐mutated non‐small cell lung carcinoma, ADCs targeting EGFR have recently emerged as promising therapeutics for patients with HER‐positive cancers." (PMID 39070179, 2024). "Combining with other keywords active at that time, the preliminary research concentrated on clinical trials and efficacy using drugs like gefitinib, cetuximab plus irinotecan, and erlotinib that target the KRAS upstream gene EGFR in cancer patients with KRAS mutations." (PMID 38706597, 2024). "Mutations in the EGFR gene are associated with various cancers, particularly in NSCLC." (PMID 38195537, 2024). "This suggested that one outcome of high SNRPD2 expression in cancer cells could be downstream activation of EGFR/MEK pathways causing resistance to EGFR and MEK inhibitors." (PMID 39684842, 2024). "Thus, patients’ cancers exhibited high expression levels of PTGS2/ESR2/EGFR/JUN/MMP2 genes’ signatures are associated with poor prognosis." (PMID 39707884, 2024). "Interestingly, our results demonstrated that when EGFR‐mutated cancer cells were exposed to CM from PCs, the effect on the sensitivity of first‐/second‐generation TKI drugs was not as pronounced as the effect on the third‐generation TKI drugs." (PMID 39435643, 2024). "In addition, we revealed that the presence of Mott cells was inversely associated with cancer stem cell markers such as CD44 or tyrosine kinase molecules such as EGFR." (PMID 38337351, 2024). "In addition, 14 out of 24 patients (58.33%) had PDL1 < 1%, and 4 (17%) had PDL1 ≥ 50%, while 29 patients (85%) had EGFR-mutated cancers, most of them (74%) with common mutations." (PMID 38610927, 2024). "Exon 19 deletion mutations account for 45% of mutations, whereas Exon 21 mutations, resulting in L858R substitutions, account for 40% to 45% of mutations that predict sensitivity to EGFR TKIs (like erlotinib, afatinib, gefitinib, and osimertinib) to slow or halt cancer cell growth." (PMID 39416762, 2024). "Subsequent functional assays showed that PCs could regulate the sensitivity of EGFR‐mutated cancer cells to TKIs through paracrine effects." (PMID 39435643, 2024).
cancer (continued). "Similarly, in targeted cancer therapies, ROS-mediated tumor cell death is also universal and closely linked to the development of drug resistance, such as ROS and EGFR." (PMID 38982494, 2024). "Receptor tyrosine kinases (RTKs) that respond to the Epidermal Growth Factor (EGF) family of ligands play important roles in development and physiology across metazoa, and dysregulation of EGF receptor (EGFR/ErbB) signaling is associated with several human cancers." (PMID 38545437, 2024). "Given that the PC9 cells contain an activating mutation in EGFR, we hypothesized that EGFR inhibitors act on the cancer cells to prime them for macrophage-mediated destruction." (PMID 38483480, 2024). "Notably, one of the most mutated and/or overexpressed GF receptor in cancer, the EGFR, is also one of the most abundantly receptors co-opted by viruses, for their transfection into host cells." (PMID 38526562, 2024). "Furthermore, since EGFR is mutationally activated in some human cancers, we transfected a common mutant – EGFR L858R – into RNF43 WT vs. KO HT29 cells and compared the resulting protein levels." (PMID 38260423, 2024). "However, mutations in the EGFR gene are linked to various cancers, including non‐small cell lung cancer (NSCLC), gallbladder cancer, and glioblastoma." (PMID 39358807, 2024). "KEGG signaling pathway analysis showed that AS-IV was associated with EGFR tyrosine kinase inhibitor resistance, proteoglycans and pathways in cancer, chemical carcinogenesis-receptor activation, endocrine resistance, and PI3K/AKT signaling pathway was also highly correlated." (PMID 38689349, 2024). "Furthermore, the utilization of the clinically approved Src inhibitor Dasatinib can counteract the suppressive paracrine effect of PCs on the sensitivity of third‐generation TKIs in EGFR‐mutated cancer cells." (PMID 39435643, 2024). "In addition to gene mutation(s), increased EGFR protein expression plays a critical role in regulating cancer development.The upregulation of EGFR protein recycling, stability, or gene transcription can facilitate EGFR protein expression." (PMID 39967270, 2024). "Notably, genes identified in these metastatic patients—BAP1, BRAF, and EGFR—have been previously reported in association with cancer metastasis." (PMID 38893126, 2024). "The response of cancer cells to mechanical signals may rely on the genetic modifications that promote tumorigenesis, involving activating mutations of the Ras, EGFR, or PI3K signal transduction routes." (PMID 38201302, 2024). "Moreover, glycolysis is orchestrated by a series of glycolytic enzymes, and the dysregulation of the procedure has been implicated in conferring resistance to EGFR-targeted therapies in cancer cells." (PMID 38255882, 2024). "Therefore, this study establishes a novel synthetic scheme which will allow for the development of future clinically relevant anti-cancer molecules which can be used in combination with specific drugs targeting EGFR mutated cancers." (PMID 39193280, 2024). "Despite the development of new generations of targeted cancer therapeutics, first-generation EGFR-targeted drugs are still used against tumors with EGFR-activating mutations or EGFR-overexpressing tumors (EGFR-positive tumors), either in combination with other drugs or alone." (PMID 38201251, 2023). "Additional treatment options and cancer risk could also be found with further research, which would benefit all patients with a germline EGFR T790M mutation." (PMID 37265791, 2023). "Similarly to EGFR, AXL controls different pathways implicated in cancer cell proliferation, and has been correlated to the resistance to EGFR-targeting therapies." (PMID 37047090, 2023). "Extensive future evaluation of EGFR exon 20 insertions is needed to provide a basic database to help tailor treatment modalities for cancers with insertional mutations within EGFR exon 20, allowing more appropriate patients with EGFR 20 insertional mutations to benefit from afatinib therapy." (PMID 37366888, 2023).
cancer (continued). "Several recent studies have revealed associations of EGFR with cancer and AD; thus, regulating EGFR expression may be a strategy for treating both diseases." (PMID 37601068, 2023). "EGFR is frequently dysregulated in cancer cells by over-expression or activating mutations." (PMID 38137520, 2023). "Large fragment deletion (LFD) of EGFR was associated with carcinogenesis in many types of cancers." (PMID 36622089, 2023). "The same search was performed with the epidermal growth factor receptor (EGFR), which is mutated in several cancers, including non small cell lung cancer (NSCLC), and respective EGFR mutations were also detected in 100% of exoDNA isolated from the NSCLC cell lines, harboring EGFR mutations." (PMID 36900248, 2023). "For patients with epidermal growth factor (EGFR)-mutated cancers, EGFR inhibitors, including the third-generation tyrosine kinase inhibitor (TKI) osimertinib, significantly prolong progression-free survival and overall survival, and are the current standard of care." (PMID 37296959, 2023). "We showed that PAI-1 is involved in tolerance to osimertinib in EGFR-mutated cancer cells." (PMID 36831438, 2023). "The mechanism by which vitamin D reduces cancer risks has been attributed to the inhibition of cancer-promoting signaling pathways, including mutations in epidermal growth factor receptor (EGFR) and the dysregulation of Wnt/β-catenin, which determines proliferation and metastasis." (PMID 37047063, 2023). "We speculate that EGFR VUSs (KD +) and rare EGFR mutations are within the same cancer cell or even on the same allele, and the additional KD aberrations from the VUSs might help reinforce the oncogenic activities of rare EGFR mutations." (PMID 36829178, 2023). "EGFR is closely linked to cancer development, making it a candidate target for cancer therapy." (PMID 36674593, 2023). "However, most EGFR-mutated cancers can develop resistance caused by a T790M mutation, which can be pre-existent or appear after implementing the TKIs." (PMID 37698765, 2023). "In addition, PDPN+ CAFs induce primary resistance to EGFR tyrosine kinase inhibitor (EGFR-TKI) in LUAC with EGFR mutation by activating the MAPK signaling pathway in cancer cells." (PMID 37143134, 2023). "Osimertinib is the first FDA-approved third-generation EGFR-TKI; current therapeutic protocols allow its use for both NSCLC patients with activating EGFR mutation and patients with T790M resistance mutation cancers with encouraging results, though still limited by acquired resistance." (PMID 36979684, 2023). "Meanwhile, since droplet digital PCR (ddPCR) has a better sensitivity to detect low‐frequency mutations, we used ddPCR to analyze nine patient samples from Drum Tower Hospital to confirm the existence of cancer cell‐derived DNA fragments carrying EGFR L858R mutations in RBC." (PMID 36599687, 2023). "There are 764 'cancer or benign tumor'diseases or phenotypes associated with EGFR, predicted by the 'Open Targets Platform'.The Open Targets Platform is a powerful resource that facilitates the methodical discovery and ranking of promising targets fortherapeutic drugs." (PMID 37808374, 2023). "Although the strong association between the COX-2/mPGES-1/PGE2 pathway and EGFR and its molecular signals in cancer is widely reported, more in-depth studies are necessary to better understand the physiopathological significance and the potential for cancer therapy." (PMID 37190301, 2023). "Notably, recent studies demonstrated the transfer of EGFR and associated molecules from different cancer cells, activating pro-tumorigenic pathways in recipient cells." (PMID 37296932, 2023). "Our data suggest significantly low abundance of EGFR in non-tumorous (histologically normal) and lower abundance in tumorous compared with healthy livers, and this may indicate high risk of developing cancer in individuals with low amounts of EGFR." (PMID 36890818, 2023). "High EGFR expression is positively associated with cancer progression." (PMID 36869126, 2023).
cancer (continued). "It has been also hypothesized that the oncogenic variant of the epidermal growth factor receptor (EGFR), a well-known proto-oncogene widely overexpressed and/or amplified in human cancer, may be correlated with CBX3 expression in NSCLC." (PMID 37633946, 2023). "In addition to gene amplification of EGFR, activating mutations from EGFR are also one of the most common targetable oncogenic drivers in multiple cancers." (PMID 37528485, 2023). "In the era of precision medicine, targeted therapies have caused a revolutionary improvement in cancer management by inhibiting activating genetic alterations in the epidermal growth factor receptor (EGFR), anaplastic lymphoma kinase (ALK), and ROS1 proto-oncogene receptor tyrosine kinase (ROS1)." (PMID 36647009, 2023). "In this study, the EGFR-TKI treatment induced high PAI-1 expression in EGFR-mutated cancer cells." (PMID 36831438, 2023). "Indeed, although HNSCCs are a heterogeneous group of cancers which differ for histological, molecular and clinical features, EGFR is overexpressed or mutated in a percentage of cases up to about 90%." (PMID 36817764, 2023). "EGFR is frequently mutated to a constitutively active form in these cancers." (PMID 36602390, 2023). "Similarly, most of the genes these variants locate on are associated with one (20.86%) or two (55.83%) indications, with exceptional BRAF, ERBB2, KRAS and EGFR associated with >10 types of cancer indications." (PMID 36856726, 2023). "Thus, we conclude that Arl4A also participates in endolysosomal delivery and degradation of cancer-associated EGFR mutants." (PMID 38030597, 2023). "KRAS and EGFR mutations are common in this form of cancer and can influence treatment response." (PMID 37508774, 2023). "Patients confirmed to have EGFR p.T790M PGVs appear to have roughly a 23% increased risk of LC, and screening for LC might be considered in these patients and for other cancers if proven to be EGFR-associated." (PMID 37992258, 2023). "EGFR gene mutation and amplification have been shown to be crucial drivers of many cancer types." (PMID 37587470, 2023). "EGFR signaling is frequently hijacked by cancer cells to promote oncogenesis, mainly through EGFR gene amplification and/or overexpression, in addition to a variety of activating mutations in different types of human cancers." (PMID 37766136, 2023). "Recently approved in May 2020 for LC therapy, ramucirumab can be used with erlotinib when an activating mutation of EGFR is present in cancer cells." (PMID 37698765, 2023). "Osimertinib was the first FDA and EMA-approved third-generation EGFR-TKI which received marketing authorization in the first-line for patients with advanced tumors harboring activating EGFR mutations and for patients whose cancer cells show T790M mutations after prior EGFR-TKI treatments." (PMID 37444638, 2023). "Additionally, nuclear EGFR has been associated with therapy resistance to targeted therapy and histone deacetylase inhibitors in different cancers." (PMID 37415208, 2023). "Regression to cancer is often the result of driver mutations in the EGFR gene itself, preventing drug binding to the ATP-binding pocket and reactivating the EGFR signaling pathways suppressed by the corresponding TKIs, which can lead to metastatic manifestations in the patient." (PMID 37754201, 2023). "Through the activation of various intracellular signaling pathways such as RAS‐MAPK, PI3K‐Akt, and cyclin‐dependent kinases (CDKs), EGFR overexpression and mutations (Most are deletions in exon 19 or L858R in exon 21) confer a dysregulated and/or constitutive proliferative activity to cancer cells." (PMID 37341071, 2023). "Furthermore, we demonstrated that the combination of osimertinib with a PAI-1 inhibitor prevented the regrowth of osimertinib-treated tumors composed of EGFR-mutated cancer cells in in vivo experiments." (PMID 36831438, 2023).